DMRT2 (doublesex and mab-3 related transcription factor 2)
Description:
Transcriptional activator that directly regulates early activation of the myogenic determination gene MYF5 by binding in a sequence-specific manner to the early epaxial enhancer element of it. Involved in somitogenesis during embryogenesis and somite development and differentiation into sclerotome and dermomyotome. Required for the initiation and/or maintenance of proper organization of the sclerotome, dermomyotome and myotome (By similarity).
Synonyms: DSXL-2; SCDO7
Tractability: No criterion of Open Targets' tractability assessment is met for any kind of drug.
Gene: Protein-coding gene on chromosome 9 (1,049,000 to 1,057,563, forward strand). Ensembl gene ENSG00000173253.
Subcellular location: Nucleus
Subcellular location (Human Protein Atlas): Nucleoli; Nucleoplasm; Centriolar satellite; Vesicles
Gene Ontology:
Molecular function: protein binding; DNA-binding transcription factor activity, RNA polymerase II-specific; RNA polymerase II cis-regulatory region sequence-specific DNA binding; DNA-binding transcription activator activity, RNA polymerase II-specific; double-stranded DNA binding; identical protein binding; RNA polymerase II transcription regulatory region sequence-specific DNA binding; sequence-specific DNA binding
Biological process: regulation of transcription by RNA polymerase II; sex differentiation; positive regulation of transcription by RNA polymerase II; regulation of DNA-templated transcription
Cellular component: chromatin; nucleus
Genetic constraint (gnomAD): Loss-of-function variants: 33 observed, 34.51 expected, observed/expected ratio (o/e) 0.96, 90% interval 0.72 to 1.28. The synonymous counts are far from expectation, so gnomAD's model fits this gene poorly and the ratio says little. Missense variants: 1,064 observed, 681.94 expected, observed/expected ratio (o/e) 1.56, 90% interval 1.48 to 1.64. Synonymous variants: 395 observed, 269.01 expected, observed/expected ratio (o/e) 1.47, 90% interval 1.35 to 1.6.
Homologues: Orthologues: chimpanzee DMRT2 (98% identical), macaque DMRT2 (96% identical), rabbit DMRT2 (88% identical), dog DMRT2 (87% identical), pig DMRT2 (86% identical), rat Dmrt2 (84% identical), mouse Dmrt2 (84% identical), guinea pig DMRT2 (82% identical), tropical clawed frog dmrt2 (59% identical), zebrafish dmrt2a (51% identical), Drosophila melanogaster dmrt11E (20% identical), Caenorhabditis elegans dmd-7 (14% identical), and 1 more. Paralogues in human: DMRTA1 (20% identical), DMRT3 (18% identical), DMRTA2 (18% identical), DMRT1 (17% identical), DMRTB1 (14% identical), DMRTC2 (13% identical), DMRTC1 (5% identical), DMRTC1B (5% identical).
Diseases named in the same sentence as DMRT2 in open-access papers:
DMRT2 is named in the same sentence as 21 diseases in open-access papers, as found by Europe PMC text mining. Sharing a sentence is not in itself a finding about the gene and the disease. The quoted sentences say what the papers report.
neuroblastoma (3 papers, 2021 to 2025). Neuroblastoma (NB) is the most common solid, extracranial childhood tumor. "While no studies have specifically identified the neuronal function of DMRT2, one report conducted in human neuroblastoma cells shows that DMRT2 regulates both the proliferation rate and the progression of tumor growth." (PMID 41165867, 2025). "Another piece of literature revealed a role for circ-CUX1 in accelerating neuroblastoma progression through the miR-16-5p/DMRT2 pathway." (PMID 38282862, 2024). "Indeed, in vitro studies in neuroblastoma cell lines have shown that human DMRT2 expression is regulated by miR-16-5p." (PMID 41165867, 2025).
Obesity (3 papers, 2020 to 2023). Accumulation of substantial excess body fat. "A total of 175 genes including thermogenic markers (UCP2, CKMT2, and CITED1) and 5 BATLAS markers (PPARGC1B, ACO2, ACSF2, NNAT, and DMRT2) were expressed less in active beige adipocytes carrying FTO obesity-risk variant as compared to risk-free carriers." (PMID 37416800, 2023). "Importantly, we identified four genes (CSN1S1, DMRT2, DMRT3 and HOXA5) as novel candidate genes of body fat distribution pattern in Africans, whose biological function and implication in the pathogenesis of obesity-associated metabolic diseases remain to be unravelled." (PMID 32581226, 2020). "According to GSE12050, DMRT2 expression was significantly downregulated in subcutaneous adipose tissue from subjects with obesity compared with non-obese." (PMID 35250844, 2021).
breast carcinoma (2 papers, 2013 to 2017). "Furthermore, we identified several unreported tissue-specific TFs that may contribute to breast cancer, including ATOH8, DMRT2, TBX15 and ZNF367." (PMID 28036274, 2017). "In addition, this study found the following tissue specific TFs that were not reported in breast cancer: ATOH8, DMRT2, TBX15 and ZNF367." (PMID 28036274, 2017).
Endotoxemia (2 papers, 2021 to 2024). "Linc-DMRT2, which is transcribed from the DMRT2 gene, is decreased within the adipose tissues of patients with inflammation-induced cardiometabolic diseases, and the level of linc-DMRT2 is closely related to lipopolysaccharide (experimental endotoxemia) in the blood." (PMID 35250844, 2021).
gonadal dysgenesis (1 paper, 2018). A congenital disorder characterized by the presence of extremely hypoplastic gonads preventing the development of secondary sex characteristics. "In addition, patients with partial duplications of Xp (including the NR0B1 gene) and chromosome 9p deletions (involving the DMRT1 and DMRT2 genes) may also present with isolated 46,XY complete gonadal dysgenesis (CGD)." (PMID 28836496, 2018).
Insulin resistance (1 paper, 2021). Increased resistance towards insulin, that is, diminished effectiveness of insulin in reducing blood glucose levels. "DMRT2 reduced insulin resistance via modulating FXR expression and transcription activity in adipocytes." (PMID 35250844, 2021). "To further confirm the improving effects of DMRT2 overexpression on HFD-induced insulin resistance of mice, we established the insulin resistance model of adipocytes by the dexamethasone induction method." (PMID 35250844, 2021). "DMRT2 overexpression significantly improved HDF-induced insulin resistance and inflammation in mice." (PMID 35250844, 2021). "DMRT2 overexpression significantly attenuated HDF-induced insulin resistance and inflammation in mice." (PMID 35250844, 2021). "DMRT2 overexpression was achieved in the mouse model and the effects of DMRT2 on mice insulin resistance were examined." (PMID 35250844, 2021). "In differentiated mouse 3T3-L1 adipocytes, FXR knockdown enhanced insulin resistance and attenuated the effects of DMRT2 overexpression upon 3T3-L1 adipocyte insulin resistance." (PMID 35250844, 2021). "In both control and insulin-resistant differentiated mouse 3T3-L1 adipocytes, FXR knockdown enhanced the insulin resistance and attenuated the effects of DMRT2 overexpression upon 3T3-L1 adipocyte insulin resistance." (PMID 35250844, 2021). "Considering the findings in the present study, DMRT2 may participate in insulin resistance by regulating the metabolic process of adipocytes." (PMID 35250844, 2021). "The HFD caused impaired glucose tolerance, which showed to be dramatically weakened by DMRT2 overexpression; HFD increased insulin resistance, which was markedly rescued by DMRT2 overexpression." (PMID 35250844, 2021). "DMRT2 interacts with FXR and improves insulin resistance in adipocytes." (PMID 35250844, 2021).
intellectual disabilities (1 paper, 2025). "Whether DMRT2 mutations contribute to human intellectual disabilities through an aberrant development of the cingulate cortex will be of significant interest to investigate further." (PMID 41165867, 2025). "Although little is known about the function of DMRT2 in the human brain, several studies have shown that deletion or duplication of the short arm of chromosome 9, where DMRT1, DMRT2, and DMRT3 are located, is associated with several mental disorders or intellectual disabilities." (PMID 41165867, 2025).
Macrocephaly (1 paper, 2021). Occipitofrontal (head) circumference greater than 97th centile compared to appropriate, age matched, sex-matched normal standards. "Additionally, mosaic duplication involving the DOCK8, DMRT1, DMRT2, DMRT3, and KANK1 genes were observed in patient 2, which may explain the presence of macrocephaly in this patient." (PMID 33455084, 2021).
sarcoma (1 paper, 2013). A usually aggressive malignant neoplasm of the soft tissue or bone. "As differentiation markers for the UPS/MFS cluster (sarcoma cluster 4) DMRT2, ZNF217 and CDKN2A were selected for comparison with sarcoma cluster 1 (mainly DDLS samples), sarcoma cluster 2 (LMS samples) and sarcoma cluster 4 (mainly PLS samples), respectively." (PMID 24345474, 2013).
tumor (5 papers, 2013 to 2025). "Further research revealed that, in NB cells, DMRT2 was the target of miR-16-5p; the DMRT2 effects on the tumor cells proliferation, migration, invasion, and glycolysis can be reversed by miR-16-5p overexpression." (PMID 37091173, 2023).
adenocarcinoma (1 paper, 2014). A common cancer characterized by the presence of malignant glandular cells. "Three genes (DSC3, KRT6A and DMRT2) were predicted as targets of miR-375, the miRNA upregulated in adenocarcinoma, and these genes were consistently down-regulated in this histological subtype." (PMID 24625834, 2014).
DMRT2 also shares sentences with these, for which no sentence is quoted: clear cell renal cell carcinoma (2 papers); carcinosarcoma (1); COVID-19 (1); mental disorder (1); metabolic disease (1); Peyronie disease (1); renal cell carcinoma (1); spondylocostal dysostosis (1); spondylothoracic dysostosis (1); testicular hypoplasia (1).